CPT1C (carnitine palmitoyltransferase 1C)
Diseases named in the same sentence as CPT1C in open-access papers (continued):
Sharing a sentence is not in itself a finding about the gene and the disease.
cancer (continued). "Moreover, the knockdown of CPT1C in human pancreatic epithelioid carcinoma also affects mitochondrial function and disrupts cellular energetic homeostasis, thereby contributing to the senescent phenotype of the cancer cells." (PMID 39596847, 2024). "In addition, deletion of the novel biomarker CPT1C induced mitochondrial dysfunction, leading to senescence-like growth inhibition and cellular senescence in six cancer cell types, including pancreatic cancer cells, and inhibited cancer growth in vivo." (PMID 37680899, 2023). "However, the molecular role played by CPT1C in cancer cells is controversial." (PMID 36693836, 2023). "However, the detailed role or CPT1C in cancer remains indefinite." (PMID 36230659, 2022). "Therefore, the putative role of CPT1c may confer cancer cells resistance to glucose- and oxygen-deprivation and serves as a promising therapeutic target." (PMID 34803493, 2021). "Studies have found that many of the key mediators of FAO, such as CD36, CPT1 (including CPT1A, CPT1B and CPT1C) and CPT2, are overexpressed in a variety of malignant tumors, and FAO has been found to be enhanced in a variety of cancers." (PMID 40514365, 2025). "The miR-377-3p/CPT1C axis is necessary for HCC, as miR-377-3p suppresses FAO by preventing the transport of FAs and reduces further energy production in cancer cells through repression of CPT1C." (PMID 38833109, 2024). "Altogether, those findings lead us to conclude that CPT1C, more than just an enzyme that facilitates FA transport to the mitochondria for FAO, plays a more general role in cancer cells." (PMID 36693836, 2023). "Sustained CPT1C expression contributes to the metabolic preference of FAO, epithelial-mesenchymal transition (EMT) phenotypes, migration, invasion, and cancer stemness in BLBC, which is mediated by modulating the redox status." (PMID 35936710, 2022). "Carnitine palmitoyltransferase 1C (CPT1C) is a member of CPT1 family and plays a key role in cancer development and progression." (PMID 35057851, 2022). "To our knowledge, we first uncovered the novel roles of CPT1C in regulating EMT, cellular motility, cancer stemness, and metastasis." (PMID 35936710, 2022). "Therefore, CPT1C may be a promising target for the treatment of cancer." (PMID 33688464, 2021). "Carnitine palmitoyltransferase 1C (CPT1C) has a vital role in mitochondrial energy metabolism and modulation of cancer cell proliferation." (PMID 32641987, 2020). "Carnitine palmitoyltransferase 1C (CPT1C) is an isoform of CPT1A with minimal catalytic activity and is expressed in the brain and many cancer cells." (PMID 30081476, 2018). "Carnitine palmitoyltransferase 1 C (CPT1C) is a pseudoenzyme exclusively expressed in neurons and cancer cells." (PMID 29725060, 2018). "We argue, therefore, that CPT1C expression in cancer cells is not a direct regulator of fat burn, but rather is a regulator of lipid metabolic reprograming and cell adaptation to environmental stressors." (PMID 36693836, 2023). "Accordingly, enhanced levels of HIF1α, which plays a fundamental role in cancer hypoxia adaptation driving transition from oxidative to glycolytic metabolism correlate with lower expression of FAO-related genes, but activates CPT1C expression." (PMID 36693836, 2023). "Subsequent studies have reported FAO changes resulting from CPT1C overexpression or silencing in other cancer cell lines, even though none of those studies measured the catalytic activity of the protein." (PMID 36693836, 2023). "Similar to CPT1A, carnitine palmitoyl transferase 1C (CPT1C), an enzyme located in the outer mitochondrial membrane, is involved in fatty acid transport and oxidation and in cell proliferation, a potential driver of cancer cell senescence." (PMID 37251321, 2023).
cancer (continued). "Recent studies found that cancer cells lacking the brain-specific metabolic enzyme carnitine palmitoyltransferase 1C (CPT1C) showed decreased fatty acid oxidation, reduced ATP generation and increased sensitivity to metabolic stress." (PMID 26799418, 2016). "Nevertheless, although we unveiled the prognostic and tumorigenic roles of CPT1C in CRC based on RNA-seq data from public database, it has not been externally validated in another cancer center." (PMID 37078750, 2023).
tumor (48 papers, 2009 to 2025). "CPT1C overexpression is associated with higher in vitro cell survival and in vivo tumour growth, especially in conditions of metabolic stress (hypoxia or glucose deprivation) and also with poorer overall survival." (PMID 36674468, 2023). "The first time that CPT1C was associated with tumor growth was in 2011, 9 years after its discovery as a new CPT1 isoform." (PMID 36693836, 2023). "A slow tumor growth curve was observed in CPT1C-KD cells, and knockdown of CPT1C caused a near 50% decrease both in tumor volumes and tumor weights, indicating CPT1C contributes to the tumor growth of BLBC in vivo." (PMID 35936710, 2022). "Notably, the expression level of CPT1C is positively associated with tumor stage, and metastatic patients (stage IV) show notably higher expression of CPT1C (P=0.005), indicating the potential role of CPT1C in promoting CRC metastasis." (PMID 37078750, 2023). "Given that lipid saturation changes in the plasma membrane (PM) are associated with drug chemoresistance in several tumours, we explored whether CPT1C expression could be involved in drug sensitivity loss in BC." (PMID 36674468, 2023). "Research found CPT1C was remarkably reduced in senescent cells, and silencing of CPT1C could also cause cellular senescence in tumor and suppress xenograft tumor growth." (PMID 36172157, 2022). "Furthermore, the extremely high relevance of CPT1C with clinical parameters implies that CPT1C is highly associated with tumor progression in BLBC, which is in accordance with our in vitro results and in vivo tumorigenic and metastatic mouse models." (PMID 35936710, 2022). "Tumor cells with high miR-1291 expression would be more sensitive to inhibition of proliferation and the decrease of the ability to resist metabolic pressure caused by the depletion of ERRα or CPT1C." (PMID 32641987, 2020). "Moreover, CPT1C may be a key element of mitochondrial dysfunction-associated tumor cellular proliferation and senescence and functionally differs from the other three subtypes CPT1A, CPT1B and CPT2 11,12." (PMID 32641987, 2020). "In CRC and other malignancies, ACSL1 augments mitochondrial FAO via the AMPK–Carnitine Palmitoyltransferase 1C (CPT1C)–ATP axis, thereby supporting both tumor cell proliferation and metastatic dissemination." (PMID 40951358, 2025). "Metabolic regulators such as CPT1C in CAFs also promote IL-6 secretion, inducing an immunosuppressive M2-like macrophage phenotype and supporting tumor immune evasion." (PMID 40718440, 2025). "The effects of increased CPT1C expression on tumor progression and FAO activity is well-documented in the literature." (PMID 38243318, 2024). "Tumor tissues exhibited relatively strong positive CPT1C expression, whereas most paired adjacent normal tissues showed weakly positive or negative expression." (PMID 38783346, 2024). "Next, we assessed the impact of CPT1C on oxidative phosphorylation in tumor cells using a Seahorse XF96 extracellular flux analyzer." (PMID 38783346, 2024). "Immunohistochemistry was performed on tumor tissue microarray to evaluate the expression levels of CPT1C and explore its potential clinical value." (PMID 38783346, 2024). "Given that CPT1C promoted the G1/S transition, we explored the biological function of CPT1C in malignant tumor progression by measuring the proliferative ability of tumor cells in MTS assays." (PMID 38783346, 2024). "To further demonstrate the role of CPT1C in tumor promotion, we subcutaneously injected KYSE30 cells stably overexpressing CPT1C or control cells into nude mice." (PMID 38783346, 2024). "Forced CPT1C expression enhanced the utilization of free fatty acids and facilitated tumor cell survival under low-glucose conditions." (PMID 38783346, 2024). "The samples were classified as CPT1C-high or CPT1C-low expression, and a significant difference was observed in the distributions of samples between tumor tissues and adjacent normal tissues." (PMID 38783346, 2024).
tumor (continued). "Elevated CPT1C accelerated the G1/S transition, facilitating tumor cell proliferation in vitro and in vivo." (PMID 38783346, 2024). "Silencing of CPT1C in different tumour cell lines triggers cellular senescence and mitochondrial dysfunction and inhibits tumorigenesis in vivo." (PMID 36674468, 2023). "Overall, those data indicate that CPT1C expression provides some metabolic advantage that favors tumor growth in the face of different metabolic challenges." (PMID 36693836, 2023). "Upon encountering ROS in the TME, the anti-VEGFR2 antibodies, CPT1C siRNA and 2-Deoxy-D-glucose are released, inhibiting angiogenesis, fatty acid oxidation and glycolysis pathways, killing the tumor cells by effectively blocking their energy supply." (PMID 37513992, 2023). "Recently, we found that carnitine palmitoyltransferase 1C (CPT1C) controls tumor cell proliferation and senescence via regulating lipid metabolism and mitochondrial function." (PMID 37151873, 2023). "The GEPIA web tool was used to depict the expression levels of CPT1s, including CPT1A, CPT1B and CPT1C, among different tumor stages in the TCGA cohort to evaluate the correlation between tumor stage and CPT1s expression." (PMID 37078750, 2023). "Those processes have been associated with significant lipidome changes and with lipotoxicity, demonstrating that CPT1C silencing dramatically increases the total fat content of tumour cells, and particularly of certain saturated FAs." (PMID 36674468, 2023). "Since the synthesis rate of stearate and oleate were opposite after transfection of siRNA CPT1C, we further studied the effects of stearate and oleate on tumor cell proliferation and senescence." (PMID 37151873, 2023). "Searching for transcripts involved in tumor cell metabolic transformation, Zaugg and collaborators found that 2 independent screening methods unexpectedly concurred in pointing to the Cpt1c gene." (PMID 36693836, 2023). "In the current study, 13C-metabolic flux analysis (13C-MFA) was used to explore the relationship between CPT1C and fatty acid metabolism during tumor cell senescence." (PMID 37151873, 2023). "When patients with TNBC received anthracycline treatment, ROC plotter analysis showed that pCR was less likely for low CPT1C expression than for high CPT1C expression tumours, and that the difference was significant for the node-positive group." (PMID 36674468, 2023). "The total abundance of four fatty acids were increased upon CPT1C knockdown, consistent with our previous report that CPT1C knockdown induces tumor cellular senescence via lipid accumulation." (PMID 37151873, 2023). "ADH5, NUDT7, PTGES3, D2HGDH, HAO2 and CPT1C also play regulatory roles in the pathological processes of various tumours." (PMID 36643625, 2023). "In summary, it seems that CPT1C upregulation is involved in enabling cellular adaptation to ever-changing metabolic conditions in tumor cells." (PMID 36693836, 2023). "Our study declared that miR-377-3p reversely regulated CPT1C expression to function as a tumor suppressor, using bioinformatics predication and further experimental data verification." (PMID 35057851, 2022). "Since miR-377-3p has been reported to be a tumor suppressor, and CPT1C was a target gene of miR-377-3p, we further explored the effects of the miR-377-3p/CPT1C axis on HCC cells." (PMID 35057851, 2022). "ATP production and immunofluorescence staining assays of the tumor masses further confirmed that miR-377-3p repressed FAO through CPT1C." (PMID 35057851, 2022). "Fourth, miR-377-3p inhibited tumor growth and metastasis by suppressing CPT1C-mediated fatty acid oxidation." (PMID 35057851, 2022). "CPT1C is also deemed as a contributor to tumor cell metabolic transformation and rapamycin resistance, which is significant for the growth of tumor cells under the conditions of metabolic stress." (PMID 36172157, 2022).
tumor (continued). "Western-blot analysis further indicated that the protein levels of ERRα and CPT1C were decreased in tumor samples from ST-miR1291-231 injected mice, consistent with the regulatory effects." (PMID 32641987, 2020). "The current work revealed the molecular mechanism by which miR-1291 and CPT1C synergistically regulate the proliferation and metabolism of tumor cells." (PMID 32641987, 2020). "Most recently, CPT1C was found to be a critical regulator of tumor cell proliferation and senescence through mitochondria-associated metabolic reprogramming, and is a potential novel target that controls tumor progression." (PMID 32641987, 2020). "In our previous study, mitochondrial dysfunction-mediated senescent phenotypes were observed when CPT1C was efficiently depleted in tumor cell lines." (PMID 32289751, 2020). "Collectively, these results support a crucial role of the ERRα-CPT1C pathway in the anti-tumor effect of miR-1291, and suggest a new anticancer strategy involving the miR-1291-ERRα-CPT1C axis." (PMID 32641987, 2020). "This work unravels a new role of CPT1C different from the previous ones described in tumor cells or neurons, and identifies CPT1C as a possible target in strategies aimed to improve the survival of hMSCs in regenerative medicine." (PMID 29725060, 2018). "With these findings, we demonstrate that CPT1C is expressed not only in neurons and tumor cells, but also in hMSCs." (PMID 29725060, 2018). "When CPT1C is upregulated, it increases FA consumption, and ATP production, facilitating tumor growth and survival." (PMID 29445084, 2018). "CPT1C was found to mediate the uptake of long-chain fatty acid across the mitochondrial membrane to activate β-oxidation, and promote tumor adaptation under metabolic stress conditions." (PMID 26725848, 2016). "Overexpression of CPT1C in MCF-7 cell line elevated fatty acid oxidation and ATP production to support resistance to glucose deprivation and siRNA-mediated CPT1C knockdown suppressed xenograft tumor growth." (PMID 25866768, 2015). "In another study, CPT1C gene expression is upregulated in non-small-cell lung carcinoma tumor tissue compared with matched normal lung tissue." (PMID 25866768, 2015). "Indeed, chronic stress in tumour‐bearing mice led to the upregulation of 3 proteins (Cpt1c, Faah, Abhd12) involved in lipid metabolism." (PMID 40172096, 2025). "Furthermore, CPT1C accelerated the G1/S transition and facilitated tumor proliferation in vitro and in vivo." (PMID 38783346, 2024). "We observed that CPT1C could promote G1/S transition, fatty acid utilization and tumor cell proliferation in ESCC." (PMID 38783346, 2024). "Additionally, CPT1C promoted tumor cell proliferation and survival by augmenting cellular ATP levels and preserving redox homeostasis, particularly under metabolic stress." (PMID 38783346, 2024). "Hence, we explored the influence of CPT1C on tumor cells cultured in medium containing 5 mM glucose to mimic the nutrient-restricted microenvironment, whereas the control medium contained 11 mM glucose." (PMID 38783346, 2024). "Additionally, CPT1C promotes tumor cell proliferation and survival by upregulating ATP levels and decreasing ROS levels, particularly under metabolic stress." (PMID 38783346, 2024). "CPT1C-overexpressing tumor cells exhibited a higher rate of proliferation than control cells." (PMID 38783346, 2024). "Though it has been well demonstrated that CPT1C knockdown induces cellular senescence 22, 23, 25, the relationship between CPT1C and fatty acid (FA) metabolism during tumor cell senescence induced by silencing CPT1C is unclear." (PMID 37151873, 2023). "The fact that blood tumor cell lines are those with less CPT1C expression may reflect their easy availability to nutrients in the bloodstream." (PMID 36693836, 2023).